MAGEA5P (MAGE family member A5, pseudogene)
Description:
May negatively regulates apoptosis.
Synonyms: CT1.5; MGC129526; formerly MAGE5; MAGEA5
Gene: Transcribed unprocessed pseudogene on chromosome X (152,114,599 to 152,115,540, reverse strand). Ensembl gene ENSG00000242520.
Diseases named in the same sentence as MAGEA5P in open-access papers:
MAGEA5P is named in the same sentence as 4 diseases in open-access papers, as found by Europe PMC text mining. Sharing a sentence is not in itself a finding about the gene and the disease. The quoted sentences say what the papers report.
tumor (3 papers, 2009 to 2022). "Significant tumor-specific demethylation was found in MAGEA3 (p<0.005), MAGEA12 (p<0.025), MAGEA4 (p<0.018), MAGEA1 (p<0.001), TKTL1 (p<0.025) and MAGEA5 (p<0.007)." (PMID 19997593, 2009).
MAGEA5P also shares sentences with these, for which no sentence is quoted: cancer (3 papers); melanoma (3); lung carcinoma (1).